PDGFB (platelet derived growth factor subunit B)
Diseases named in the same sentence as PDGFB in open-access papers (continued):
Sharing a sentence is not in itself a finding about the gene and the disease.
primary lymphedema (1 paper, 2017). A congenital condition that results in swelling in the arms or legs, and can occur during adolescence or adulthood. "In individuals with primary lymphedema, owing to FOXC2 loss-of-function mutations, the cause of ectopic SMC recruitment was suggested to be a consequence of induction of PDGFB expression within the capillaries." (PMID 28851707, 2017).
pseudohypoparathyroidism (1 paper, 2024). "Despite the thorough analysis, no known pathogenic variants were found in genes typically associated with Fahr’s syndrome (e.g., XRP1, PDGFRB, JAM2, PDGFB, SLC20A2, or MYORG) or pseudohypoparathyroidism (e.g., GNAS, STX16, or GNASAS1)." (PMID 39519162, 2024).
Pulmonary capillary hemangiomatosis (1 paper, 2017). Pulmonary capillary hemangiomatosis (PCH) is a rare form of pulmonary arterial hypertension (PAH, see this term) characterized by a capillary infiltration of the pulmonary interstitium, bronchioles and pleura leading to elevated pulmonary arterial resistance and right heart failure. "Of interest, increased PDGFB expression has been linked to pulmonary capillary hemangiomatosis, characterized by excessive capillary proliferation." (PMID 28275008, 2017).
rectal cancer (1 paper, 2017). A primary or metastatic malignant neoplasm that affects the rectum. "In our results, we identified interactions of high animal protein intake on rectal cancer risk with PDGFB and MMP1 genes previously implicated in inflammation-mediated pathologic processes including tumor progression." (PMID 28956832, 2017).
renal dysfunction (1 paper, 2025). "Notably, patients with CKD or renal dysfunction display changes in corresponding genes, such as a loss of the endothelial marker CDH5, an increase in ANGPT2 and PDGFB, and a reduction in ANGPT1." (PMID 40952790, 2025).
rheumatoid arthritis (1 paper, 2023). A chronic, systemic autoimmune disorder characterized by inflammation in the synovial membranes and articular surfaces. "It has been shown that PDGFB expression is associated with rheumatoid arthritis risk." (PMID 37063861, 2023).
schizophrenia (1 paper, 2016). A major psychotic disorder characterized by abnormalities in the perception or expression of reality. "The genes for platelet-derived growth factor beta (PDGFB) and PDGFB receptor (PDGFBR) may be important in the pathology of schizophrenia through interacting with the DRD2/DRD4 and NMDA receptors." (PMID 28117656, 2016).
Senile plaques (1 paper, 2018). Senile plaques are extracellular deposits of amyloid in the gray matter of the brain. "In this study, we evaluated the effects of enriched environment (EE) stimulation on spatial memory and senile plaque formation in transgenic mice PDGFB-APPSwInd (TG) that overexpress the human amyloid precursor protein, normally resulting in an increased density of senile plaques." (PMID 30319394, 2018).
thrombosis (1 paper, 2021). "Urinary PDGFB levels were higher in patients with TAPS than in those with RA (p=0.0425), with miscarriages (p=0.0144) and with thrombosis (p=0.0007)." (PMID 34489952, 2021). "On the other hand, PDGFB levels were higher in the urine of patients with OAPS than in those with TAPS (p=0.0406), APL carriers (p=0.0207), patients with miscarriages (p<0.0001), patients with thrombosis (p<0.0001), patients with RA (p=0.0002), patients with SLE (p=0.0052), and HCs (p=0.0005)." (PMID 34489952, 2021).
trachoma (1 paper, 2020). "Nevertheless, IL23A, SPARCL1, and PDGFB may be key mediators driving pathological inflammation and fibrosis in trachoma, and molecules that inhibit their action could hold therapeutic potential in preventing scarring progression." (PMID 31964744, 2020).
Type 2 diabetes (1 paper, 2021). "Type 2 diabetes is associated with increased APOE, BAX, MMP1, NFKB1, PDGFB, SPP1, and TGFB2." (PMID 35153741, 2021).
vascular malformation (1 paper, 2024). A non-neoplastic disorder that is the result of defects of vascular morphogenesis. "Furthermore, our study emphasizes that inducing or activating PDGFB signaling may be a viable therapeutic approach for treating vascular malformations." (PMID 38070064, 2024).
Vascular Tumors (1 paper, 2022). "Apart from the PI3K/AKT/MTOR and RAS/RAF/ERK signaling pathways, other signaling pathways are also involved in VAs: VEGF-A/VEGFR2 signaling and PDGFB/PDGFRB Signaling Pathway in vascular tumors (IH) and HGF [hepatocyte growth factor])/c -Met signaling in glomuvenous malformations (GVMs)." (PMID 36293054, 2022).
Venous malformation (1 paper, 2020). A vascular malformation resulting from a developmental error of venous tissue composed of dysmorphic channels lined by flattened endothelium and exhibiting slow turnover. "The decrease of PDGFB is one of the important reasons for the insufficient coverage of perivascular wall cells in venous malformations." (PMID 32867785, 2020).
venous thromboembolism (1 paper, 2025). Occlusion of the lumen of a vein by a thrombus that has migrated from a distal site via the blood stream. "Von Willebrand factor (vWF), PDGFB, HIVEP1, and GPX3 have been identified as biomarkers associated with venous thromboembolism in the VEBIOS cohort, with the associations of vWF and PDGFB replicated in FARIVE." (PMID 39940903, 2025).
tumor (273 papers, 1991 to 2026). "Taken together, these data establish that loss of IL-1 in the tumor and stroma leads to a reduction in MCPs in vivo, and this effect correlates with decreased infiltration of inflammatory monocytes into PDGFB mGBM." (PMID 37733448, 2023). "We have previously demonstrated in contrast with LPS stimulation, which induces Il1b expression in both BMDM and MG cultures, organotypic tumor slices generated by Cdkn2a loss and PDGFB overexpression only induce Il1b expression in BMDM cocultures." (PMID 37733448, 2023). "In KO mice where Il1b was absent in both the tumor and TME cells, Il1b loss prolonged the survival of PDGFB-driven tumor-bearing mice in a sex-independent manner." (PMID 37733448, 2023). "In this issue of the JCI, Chen, Giotti, and colleagues investigated loss of ll1b in the immune tumor microenvironment (TME) in GBM models driven by PDGFB expression and Nf1 knockdown." (PMID 37966120, 2023). "Staining against CD31 showed large vessel formation in good accordance with the PDGFB amplification as the tumor driver mutation (column 2)." (PMID 36358353, 2022). "Expression of PDGFB by cancer cells and that of PDGFRβ by tumor-associated stromal cells are strongly associated with lymphatic metastasis." (PMID 30018456, 2018). "Activation of the MAPK pathway by PDGFB has previously been associated with proliferation of glial cells in the brain and tumor initiation." (PMID 27806344, 2016). "Genetic deletion of Il1a/b is associated with decreased recruitment of lymphoid cells and loss-of-interferon signaling in various immune populations and subsets of malignant cells and is associated with decreased survival time of PDGFB-driven tumor-bearing mice." (PMID 37733448, 2023). "This might be caused by the tumor-produced PDGFB which promotes the disassociation of vascular smooth muscle cells (VSMCs) from the tumor vasculature." (PMID 32235327, 2020). "We induced DMGs by injecting mice with RCAS retroviruses expressing Cre recombinase, firefly luciferase, and the oncogene platelet-derived growth factor–ligand β (PDGFB) and monitored them for tumor formation by in vivo imaging." (PMID 40244686, 2025). "Instead, we observed that in both tumor and non-tumor contexts, PDGFB was most highly expressed by immune cells and was mainly present in myeloid-derived CD11b+ macrophages." (PMID 40060572, 2025). "Examining the proportions of cell types within each tumor revealed enrichments of OPCs and OLs in PDGFBwt and PDGFBΔNLS tumors, respectively, implicating nuclear PDGFB in the differentiation of OPCs to OLs." (PMID 40060572, 2025). "Surprisingly, we found that ESM1 and PDGFB are expressed in the same tumor regions, while the distributions of PDGFA and PDGFC seem to be mutually exclusive with those of PDGFB and ESM1." (PMID 39773984, 2025). "The pathogenesis of this specific neoplasia relies on the activation of the PDGFB pathway, stimulating tumor proliferation." (PMID 41189839, 2025). "Signal intensity measurements of both CSMD1 and total P65 were also determined in the tumor region of mice injected with either RCAS- PDGFB + shGL2 or RCAS- PDGFB + shCsmd1." (PMID 38561856, 2024). "The tumor-inhibiting efficacy of the compound was indeed restricted to models expressing both high PDGFB as well as high stromal PDGFRβ levels, highlighting the importance of improved knowledge on active tumoral PDGF signaling for future clinical applications." (PMID 38980580, 2024). "This encodes a fusion protein that functionally overlaps with the mature form of PDGFB and promotes tumor growth by activating the PDGFB receptor through autocrine-paracrine effects." (PMID 39600645, 2024).
tumor (continued). "Studies have confirmed that inhibiting the anoikis of GC cells can activate signaling pathways like JAK-STAT3, PI3K/AKT and PDGFB/PDGFRβ, thereby leading to epithelial–mesenchymal transition in tumor cells, and then induce tumor proliferation and metastasis." (PMID 39329635, 2024). "In these samples, both KLF7 and PDGFB exhibited up-regulation in tumor tissues compared to adjacent normal tissues." (PMID 38164176, 2024). "Based on prior studies implicating the NF-κB pathway in IL-1β–mediated signal transduction, we analyzed this pathway in PDGFB and Nf1 mGBM tumor cell cultures in vitro." (PMID 37733448, 2023). "Next, to distinguish between prolonged survival reflecting Il1b loss in tumor versus TME cells, we orthotopically transplanted 30,000 cells from primary PDGFB mGBM (WT;Ntv-a mice) into the striatum of WT and Il1b–/– mice." (PMID 37733448, 2023). "In these experiments, we orthotopically transplanted PDGFB-driven primary mGBM tumor cells into the brains of wild-type (WT) mice and mice deficient in Ccl7 or Ccl8/12 expression, a scheme similar to we have shown previously for Ccl230." (PMID 37012245, 2023). "ASPSCR1::TFE3 also upregulates genes important for angiogenesis and tumor metastasis, such as PDGFB, ANGPTL2, and GPNMB17,24,25, suggesting that ASPSCR1::TFE3 plays a central role in the angiogenesis characteristic of ASPS." (PMID 37029109, 2023). "Despite the inability to precisely assess the differences between normal lung tissue and malignancies, the preliminary findings suggest increased expression of CCND2 and PDGFB in tumor tissues." (PMID 36816016, 2023). "This promotes the expression of angiogenic factors VEGFA and PDGFB, leading to an increase in tumor vascular density, and targeting this pathway for cancer therapy is effective." (PMID 37259059, 2023). "Among these are the SET domain-containing 5 (Setd5) promoter 43, the Phosphoglucokinase (Pgk1) promoter 44, which are also from the PDGFB-driven tumor and normal comparison, displaying clear differences between the tumors." (PMID 37739938, 2023). "To examine this potential explanation, we grew freshly isolated PDGFB-driven tumor cells under NSC and FBS conditions and measured MCP levels in the supernatant by ELISA at passage 1 (P1)." (PMID 37733448, 2023). "Results for RELA were very similar to those obtained comparing tumor to normal brains, whereas results for PDGFB showed fewer significant cCREs at FDR = 0.05." (PMID 37739938, 2023). "Next, we performed coculture experiments with PDGFB-driven primary tumor cells (GSCs) and BMDMs and measured both intracellular (pro–IL-1β) and secreted IL-1β." (PMID 37733448, 2023). "For diagnosing DPFS, FISH is employed with a positive criterion being the identification of a COL1A1-PDGFB fusion gene or PDGFB rearrangement in at least 10% of tumor cells." (PMID 37920823, 2023). "We found freshly sorted PDGFB tumor cells expressed higher levels of Ccl2, Ccl7, Ccl8, and Ccl12 relative to the same cells maintained in vitro (up to 6 passages) under both GSC and FBS conditions (P < 0.05)." (PMID 37733448, 2023). "IL-1β in the TME increased PDGFB-driven GBM growth by increasing tumor-derived NF-κB, expression of monocyte chemoattractants, and increased infiltration of bone marrow–derived myeloid cells (BMDMs)." (PMID 37966120, 2023). "Genetic or pharmacological inhibiting neutrophils in HCC or monocyte-deficient PDGFB-driven and Nf1-silenced GBM models extend the survival of tumor-bearing mice." (PMID 37012245, 2023). "Using a GBM xenograft model, it has been shown that RT increases myeloid infiltration, and that the increased myeloid cell presence is responsible for tumor recurrence, similarly to what was reported recently in a PDGFB-driven mouse model of GBM." (PMID 36594465, 2023). "To compare the amount of PDGFB in tumors from WT and pl-PDGFB KO mice, we established a sensitive PEA, allowing detection of low abundant PDGFB in tumor tissue lysates." (PMID 35454853, 2022).
tumor (continued). "PDGFB was detected on the basis of an HA epitope tag, demonstrating that the hypercellular area was composed entirely of HA+ tumor cells." (PMID 36139666, 2022). "In contrast, the amount of circulating tumor cells, as well as the number of liver metastases, were significantly enhanced as a result of a compromised vascular barrier in pl-PDGFB KO mice." (PMID 35454853, 2022). "There was an approximately 10-fold reduction in the PDGFB concentration detected by PEA in tumor lysates from pl-PDGFB KO mice compared to that from WT mice." (PMID 35454853, 2022). "To address the specific role of platelet-derived PDGFB in the tumor microenvironment, we have created a mouse model with conditional knockout of PDGFB in platelets (pl-PDGFB KO)." (PMID 35454853, 2022). "Depletion of platelet PDGFB reduces tumor vessel pericyte coverage, increases tumor hypoxia and metastasis." (PMID 35216427, 2022). "Because platelet granules are a crucial source of PDGFB and are constantly activated in the tumor microenvironment, they can expose tumors to a range of growth factors." (PMID 36276869, 2022). "Platelets constitute a major reservoir of platelet-derived growth factor B (PDGFB) and are continuously activated in the tumor microenvironment, exposing tumors to the plethora of growth factors contained in platelet granules." (PMID 35454853, 2022). "ECs secrete platelet-derived growth factor subunit B (PDGFB) to promote pericyte recruitment to the tumor vasculature." (PMID 36389685, 2022). "Further investigation manifested that CECR1 function in (M2-like) macrophages mediated cross-talk between macrophages and pericytes in GBM via paracrine PDGFB–PDGFRβ signaling, promoting pericyte recruitment and migration, and tumor angiogenesis." (PMID 35600367, 2022). "In SCG, the primary tumor site was correlated with expression levels of PDGFB and PDGFRB (P < 0.05)." (PMID 33524869, 2021). "Quantitative PCR was used to examine the effects on mRNA levels of platelet-derived growth factor (PDGFB), tumor vascular marker CD105, and cell adhesion molecules ITGA5, ITGB1, and CD44." (PMID 34176441, 2021). "Enhanced DLK1 levels in PDGFB + DLK-A tumors were confirmed by co-staining with the tumor marker Olig2." (PMID 32205867, 2020). "Next, we employed fluorescent microscopy to visualize the suppression of IDH1R132H transgene expression by examining tumor cells transduced with mCherry–PDGFB, which expresses the fluorescent mCherry and PDGFB upon P2A cleavage." (PMID 30416682, 2018). "In accordance with the incompatibility between IDH1R132H heterozygosity and anchorage-independent growth, we observed the strong antagonism between IDH1R132H expression and PDGFB-driven tumor growth." (PMID 30416682, 2018). "Here, we showed that Lrig1 was a haploinsufficient tumor suppressor of PDGFB-induced experimental diffuse glioma in mice." (PMID 29391393, 2018). "The combination injection sets were compared to the rates of tumor formation for the PDGFB alone cohort." (PMID 27074575, 2017). "Our data is consistent with PTN enhancing PDGFB-induced tumor formation through a PTPRz-dependent increase in Akt activation." (PMID 27806344, 2016). "High level (148 fold, p < 0.05) of NG2 was also detected by Western blot assays using tumor (n = 3) and normal (n = 3) brainstem specimens obtained from PDGFB mouse model or healthy controls." (PMID 25987129, 2015). "Target analysis also revealed that PDGFB is potentially targeted by many miRs in the study that together with PDGFR amplification provides a mechanism to potentiate tumor growth." (PMID 24438171, 2014). "In contrast, using the pSico or PDGFB-iCreER-inducible systems we have deleted Rac1, predominantly, in adult tumor or VEGF-induced neo-endothelial cells themselves, thus reducing any side effects on the whole vasculature." (PMID 20339539, 2010). "Of note, a second tumor with focal MET amplification, GBM.18, was classified here and showed extremely high levels of PDGFB and associated signaling." (PMID 19915670, 2009).